ROMO1 (reactive oxygen species modulator 1)
Description:
Induces production of reactive oxygen species (ROS) which are necessary for cell proliferation. May play a role in inducing oxidative DNA damage and replicative senescence. May play a role in the coordination of mitochondrial morphology and cell proliferation. Has antibacterial activity against a variety of bacteria including S.aureus, P.aeruginosa and M.tuberculosis. Acts by inducing bacterial membrane breakage.
Synonyms: MTGM; C20orf52; bA353C18.2; MTGMP
Tractability: Antibody: UniProt predicts a signal peptide or a membrane-spanning region. PROTAC: its protein half-life has been measured.
Gene: Protein-coding gene on chromosome 20 (35,699,254 to 35,700,984, forward strand). Ensembl gene ENSG00000125995.
Subcellular location: Mitochondrion inner membrane
Gene Ontology:
Molecular function: monoatomic cation transmembrane transporter activity; protein binding
Biological process: antibacterial innate immune response; cellular response to reactive oxygen species; defense response to bacterium; defense response to Gram-negative bacterium; defense response to Gram-positive bacterium; monoatomic cation transmembrane transport; positive regulation of reactive oxygen species metabolic process; protein insertion into mitochondrial inner membrane; replicative senescence; intracellular protein transport; protein import into mitochondrial matrix
Cellular component: mitochondrial inner membrane; mitochondrion; TIM23 mitochondrial import inner membrane translocase complex
Genetic constraint (gnomAD): Loss-of-function variants: 8 observed, 7.83 expected, observed/expected ratio (o/e) 1.02, 90% interval 0.6 to 1.74. That is too few expected variants to judge how well the gene tolerates losing a copy. Missense variants: 91 observed, 117.59 expected, observed/expected ratio (o/e) 0.77, 90% interval 0.65 to 0.92. Synonymous variants: 41 observed, 42.95 expected, observed/expected ratio (o/e) 0.95, 90% interval 0.74 to 1.24.
Homologues: Orthologues: chimpanzee ROMO1 (100% identical), dog ROMO1 (100% identical), guinea pig ROMO1 (100% identical), macaque ROMO1 (100% identical), mouse Romo1 (100% identical), pig ROMO1 (100% identical), rabbit ROMO1 (100% identical), rat Romo1 (100% identical), tropical clawed frog romo1 (95% identical), zebrafish romo1 (91% identical).
Diseases named in the same sentence as ROMO1 in open-access papers:
ROMO1 is named in the same sentence as 52 diseases in open-access papers, as found by Europe PMC text mining. Sharing a sentence is not in itself a finding about the gene and the disease. The quoted sentences say what the papers report.
colorectal cancer (9 papers, 2017 to 2025). A primary or metastatic malignant neoplasm that affects the colon or rectum. "For example, in colorectal cancer and hepatocellular carcinoma, ROMO1 overexpression has been linked to tumor progression, increased migration, and poor prognosis." (PMID 41148844, 2025). "In hepatocellular carcinoma, colorectal cancer, and breast cancer, overexpression of ROMO1 has been associated with enhanced tumor cell proliferation, migration, and invasion, often linked to ROS-mediated activation of MAPK and NF-κB pathways." (PMID 41148844, 2025). "For example, ROMO1 has been associated with poor prognosis in colorectal cancer patients, and poor survival in non-small cell lung cancer (NSCLC) patients." (PMID 39727991, 2024). "Romo1 overexpression in tumor tissue was significantly associated with survival in curatively resected colorectal cancer patients, suggesting Romo1 expression as a potential adverse prognostic marker." (PMID 28472059, 2017). "For the first time, we investigated the association between Romo1 and the clinical outcomes of colorectal cancer patients." (PMID 28472059, 2017). "Lung, colorectal cancer and gliomas have been linked to ROMO1." (PMID 33302957, 2020). "We conducted survival analyses for patients who had curative resection (n = 190) in accordance with clinical parameters including level of Romo1 expression, and we examined the association between Romo1 expression and cell invasion using Matrigel invasion assay in colorectal cancer cells." (PMID 28472059, 2017). "We present evidence that targeting the Romo1-Bax pathway can provide therapeutic benefits for treatment of colorectal cancer." (PMID 32825500, 2020). "Cell invasiveness decreased in the Romo1 knockdown colorectal cancer cells in contrast to the controlled cells." (PMID 28472059, 2017). "In bladder cancer for instance, the miR-4492/ROMO1 axis controls the proliferation, migration, and invasion of cancer cells, while the miR-4492/FOXK1 axis has been implicated in the proliferation and invasion of colorectal cancer cells." (PMID 38261743, 2024). "In addition, through controlling the generation of ROS, ROMO1 inhibition significantly triggered the apoptotic cell death in colorectal cancer cells." (PMID 37386404, 2023). "In this paper, we suggest that targeting Romo1 is essential for the treatment of colorectal cancer and may be a new therapeutic strategy." (PMID 32825500, 2020). "In colorectal cancer, ROMO1 expression predicts poor survival and higher invasiveness." (PMID 33302957, 2020). "Moreover, the expression of endogenous Romo1 was elevated in colorectal cancer cell lines comparing normal colon cell lines." (PMID 32825500, 2020). "We suggest that targeting of Romo1 is essential for the treatment of colorectal cancer and may be a new therapeutic approach in the future and contribute to the drug discovery." (PMID 32825500, 2020). "Romo1 is a mitochondrial inner membrane channel protein that controls reactive oxygen species (ROS) production, and its expression is highly upregulated in various cancers, including colorectal cancer." (PMID 32825500, 2020). "The findings of our study highlight a mechanism by which Romo1-dependent ROS generation may regulate apoptosis through Bax activation in colorectal cancer." (PMID 32825500, 2020). "We have demonstrated that Romo1 inhibition and TRAIL have a combined effect in colorectal cancer and identified the novel mechanism of this combined effect associated with the TRAIL pathway." (PMID 32825500, 2020). "There are several studies that have reported ROMO1 expression in different cancer cells: colorectal cancer, non-small cell lung cancer, hepatocellular carcinoma, and cervical cancer." (PMID 40427422, 2025). "Studies have shown that ROMO1 is overexpressed in hepatocellular carcinoma, colorectal cancer, and glioma but has not been reported in PCa." (PMID 34996995, 2022).
colorectal cancer (continued). "In the present study, we demonstrated that Romo1 inhibition significantly increased TRAIL-induced apoptosis of colorectal cancer cells, but not of normal colon cells." (PMID 32825500, 2020). "Our study suggests that targeting Romo1 may have strong anti-cancer effect as a sensitizer of TRAIL-based therapy and may contribute to improving the development of novel medicines for colorectal cancer." (PMID 32825500, 2020).
hepatocellular carcinoma (9 papers, 2017 to 2025). A malignant tumor that arises from hepatocytes. "Recent studies have implicated ROMO1 in various types of cancer, including hepatocellular carcinoma, colorectal, prostate, gastric, bladder, lung, and glioma." (PMID 39727991, 2024). "Moreover, oxidative stress-induced Romo-1 expression is associated with tumor cell invasion via NF-κB signaling has been reported to increase constitutive activation of NF-κB in hepatocellular carcinoma." (PMID 35461390, 2022). "A study conducted in 2012, where 95 patients were enrolled, explored the link between ROMO1 expression, mitochondrial ROS production, and cancer cell invasiveness, particularly in hepatocellular carcinoma (HCC)." (PMID 40427422, 2025). "Another study has shown that ROMO1 and the NF-κB pathway may regulate oxidative stress-induced tumor cell invasion in hepatocellular carcinoma." (PMID 39727991, 2024). "A previous study suggested that Romo1 overexpression induces tumor invasion and contributes to poor prognosis in patients with hepatocellular carcinoma (HCC)." (PMID 28472059, 2017).
non-small cell lung carcinoma (6 papers, 2017 to 2024). A group of at least three distinct histological types of lung cancer, including non-small cell squamous cell carcinoma, adenocarcinoma, and large cell carcinoma. "MGR2/ROMO1 is involved in protein import into the mitochondrial matrix and overexpression of ROMO1 has been associated with poor prognosis in colorectal and non-small cell lung cancer patients." (PMID 31660150, 2019). "In non-small cell lung cancer ROMO1 can serve as disease biomarker and is a predictor of poor survival and malignant effusions in these patients." (PMID 33302957, 2020). "Interestingly, the cell proliferation related to Romo1 overexpression that was demonstrated in cancers including non-small-cell lung cancer, cervical cancer, basal cell carcinoma, and HCC was also not observed in the present study." (PMID 28472059, 2017).
cervical cancer (4 papers, 2017 to 2025). A primary or metastatic malignant neoplasm involving the cervix. "The impetus for this review emerged from our own clinical research on ROMO1 expression in cervical cancer." (PMID 41148844, 2025). "ROMO1 shows potential as a biomarker for disease stage and mitochondrial dysfunction in HPV-associated lesions, particularly cervical cancer." (PMID 41148844, 2025). "An immunohistochemical study in cervical cancer (CC) patients found significantly higher ROMO1 expression in early-stage tumors (FIGO I) compared to advanced stages (FIGO II/III)." (PMID 41148844, 2025). "In an initial cohort of 75 patients with confirmed cervical carcinoma, we observed an interesting pattern: ROMO1 expression was highest in early-stage tumors and progressively decreased as the disease advanced." (PMID 41148844, 2025). "We also highlight our own emerging data, suggesting that ROMO1 expression is biphasic in cervical cancer—a pattern that differs from other tumor types and may reflect virus-specific regulation." (PMID 41148844, 2025). "In invasive cervical carcinomas, ROMO1 expression was heterogeneous." (PMID 41515519, 2025). "For the detection of early-stage cervical carcinoma and high-grade precancerous lesions, ROMO1 may be a useful auxiliary biomarker." (PMID 41515519, 2025). "Notably, ROMO1 expression was highest in stage I tumors and declined in more advanced stages of cervical carcinoma." (PMID 41515519, 2025). "Unlike in other cancers where ROMO1 tracks aggressiveness, in cervical cancer its decline reflects viral reprogramming and metabolic adaptation." (PMID 41515519, 2025). "Our findings simply show that ROMO1 does not track with disease severity in cervical cancer in the way it does in HPV-independent tumors." (PMID 41515519, 2025). "A previous report showed that ROMO1 siRNA transfection effectively decreased ROS levels in human cervical cancer cells, human lung carcinoma cells, and human non-transformed lung fibroblast cells." (PMID 34915903, 2021). "There is currently a lack of thorough information regarding the expression of ROMO1 in normal vs. precancerous lesions and in cervical cancer, as well as on whether or not its expression is correlated with the severity of the disease." (PMID 41515519, 2025). "The observation is noteworthy, however, and suggests that ROMO1 may not behave uniformly across all cervical cancer types." (PMID 41515519, 2025). "Clarifying the pattern of ROMO1 expression in cervical neoplasia could provide new insights into HPV-related carcinogenic mechanisms and identify a novel biomarker to improve the specificity of cervical cancer diagnostics in the era of HPV-driven screening." (PMID 41515519, 2025). "There is currently a lack of thorough information regarding the expression of ROMO1 in normal vs. precancerous lesions and cervical cancer, as well as on whether or not its expression is correlated with the severity of the disease." (PMID 41515519, 2025).
glioma (4 papers, 2020 to 2024). A benign or malignant brain and spinal cord tumor that arises from glial cells (astrocytes, oligodendrocytes, ependymal cells). "In glioma, knockdown of ROMO1 inhibited the cell cycle progression and cell growth by decreasing cellular ROS production." (PMID 37386404, 2023). "ROMO1 has been indicated to regulate ROS production and cell growth in gliomas." (PMID 39727991, 2024).
lung carcinoma (4 papers, 2020 to 2021). "Romo1 has been shown to be associated with poor survival in various clinical settings for the treatment of lung cancer." (PMID 34956890, 2021). "Studies have consistently demonstrated the potential value of Romo1 as a novel biomarker for various lung cancer treatment." (PMID 34956890, 2021). "Summary of studies on the predictive and prognostic value of Romo1 in lung cancer." (PMID 34956890, 2021).
Sepsis (4 papers, 2020 to 2023). Sepsis is defined as life-threatening organ dysfunction caused by a dysregulated host response to infection. "In a previous study, we suggested that the K58–R78 domain of Romo1, a mitochondrial protein encoded by the nucleus, was a promising treatment candidate for sepsis caused by MDR bacteria." (PMID 34361008, 2021). "In this study, we explored the possibility of the pore-forming domain of Romo1 as an AMP for treating sepsis caused by MDR bacteria and showed that AMP derived from Romo1 (AMPR-11) is a promising agent for treatment of sepsis caused by MDR bacteria." (PMID 32291307, 2020). "However, only ROMO1 showed an increased risk of death outcome in children with sepsis." (PMID 37249456, 2023). "We observed concordant increased expression of the BLOC1S1 and ROMO1 mitGenes in the hypothyroidism and sepsis survivor scenarios (adult and child)." (PMID 37249456, 2023). "In our previous study, we reported that a Romo1-derived peptide (K58–R78 region of Romo1, AMPR-11) exhibited a broad spectrum of antibacterial activity with low toxicity, including in a murine model of sepsis." (PMID 34361008, 2021). "Finally, we demonstrated that ROMO1, SLIRP and TIMM8B could be predictive biomarkers in children's sepsis." (PMID 37249456, 2023). "Furthermore, some mitGenes with a concordant expression gain related to ATP production mechanism were shared between hypothyroidism and sepsis: SLIRP and TIMM8B appeared in sepsis nonsurvivor scenarios; ROMO1 and BLOC1S1 were present in both survivor and nonsurvivor scenarios." (PMID 37249456, 2023). "In adult sepsis, BLOC1S1, ROMO1, SLIRP and TIMM8B showed excellent ability to identify nonsurvivor samples." (PMID 37249456, 2023). "BLOC1S1, ROMO1, SLIRP and TIMM8B mitGenes showed the capability to distinguish sepsis survivors and nonsurvivors." (PMID 37249456, 2023).
glioblastoma (3 papers, 2020 to 2024). The most malignant astrocytic tumor (WHO grade IV). "In our preliminary study, we found that the overexpression of Romo1 is associated with the poor prognosis of glioblastoma patients." (PMID 31945745, 2020). "In our preliminary study, we found that the high expression of Romo1 is associated with the poor prognosis of glioblastoma patients and that Romo1 is highly expressed in macrophages." (PMID 31945745, 2020). "In this study, we found that the high expression of Romo1 is associated with the poor prognosis of glioblastoma patients." (PMID 31945745, 2020). "Studies in the literature have shown that ROMO1 expression is increased in cancer types such as bladder, glioblastoma, prostate, and gastric cancer." (PMID 39727991, 2024). "Collectively, our study highlights the important role of Romo1 in immune response especially the function of macrophages, and implicates it as a potential target of immunotherapy for glioblastoma." (PMID 31945745, 2020). "To reveal the relationship between Romo1 expression and the progression of glioblastoma, we extracted the mRNA levels of Romo1 in the tumor tissues of glioblastoma patients with RNA-Seq data (n=156) from the Glioblastoma Multiforme dataset of TCGA database." (PMID 31945745, 2020). "We found that the mRNA levels in glioblastoma samples were significantly higher than the mRNA levels of Romo1 in the normal brain samples (n=5, p<0.01)." (PMID 31945745, 2020). "To further study the role of immune cell expressed Romo1 in the tumorgenesis of glioblastoma, we transplanted the Romo1-lentivirus transduced or the control bone marrow cells into the recipient mice." (PMID 31945745, 2020). "To confirm the relationship between the Romo1 overexpression of macrophages and the progression of glioblastoma, we constructed the mouse model with Romo1 overexpression in bone marrow cells and on this basis established the glioblastoma mouse model." (PMID 31945745, 2020). "These indicated that the overexpression of Romo1 in bone marrow cells could suppress the T cell response in glioblastoma." (PMID 31945745, 2020). "Through the orthotopic glioblastoma mouse model, we also found that the overexpression of Romo1 in bone marrow cells inhibited the immune response within tumor microenvironment, implicating that Romo1 may also participate in the immune tolerance of tumor." (PMID 31945745, 2020). "In addition, the inhibition of Romo1 combining with anti-PD-1 immunotherapy significantly improved the survival outcome of glioblastoma in mouse model." (PMID 31945745, 2020). "We further investigated the potential of Romo1 as the target of glioblastoma immunotherapy." (PMID 31945745, 2020). "The synergistic effect also suggested that the inhibition of Romo1 in bone marrow cells could enhance the efficacy of anti-PD-1 immunotherapy for glioblastoma." (PMID 31945745, 2020). "We found that when the expression of Romo1 in bone marrow cells was knocked down, the tumor growth of glioblastoma was significantly inhibited (Control shRNA vs. Romo1 shRNA, p<0.01), while the disease latency was significantly prolonged (Control shRNA vs. Romo1 shRNA, p<0.05)." (PMID 31945745, 2020). "Although several studies indicated that Romo1 may directly promote the tumor growth or metastasis, our study showed that the overexpression of Romo1 seemed to specifically occurred in monocytes/macrophages within tumor microenvironment of glioblastoma." (PMID 31945745, 2020). "Further study revealed that Romo1 is highly expressed in macrophages, indicating that the overexpression of Romo1 may participate in the function of macrophages and contribute to the progression of glioblastoma." (PMID 31945745, 2020).
glioblastoma (continued). "Furthermore, our study showed that the combination of Romo1 inhibition and PD-1 blockade significantly improved the survival outcome of glioblastoma in mouse model, implicating that Romo1 may have an important role in regulating the crosstalk between tumor-associated macrophages and T cells." (PMID 31945745, 2020).